LRAT (lecithin retinol acyltransferase)
Description:
Transfers the acyl group from the sn-1 position of phosphatidylcholine to all-trans retinol, producing all-trans retinyl esters. Retinyl esters are storage forms of vitamin A (Probable). LRAT plays a critical role in vision (Probable). It provides the all-trans retinyl ester substrates for the isomerohydrolase which processes the esters into 11-cis-retinol in the retinal pigment epithelium; due to a membrane-associated alcohol dehydrogenase, 11 cis-retinol is oxidized and converted into 11-cis-retinaldehyde which is the chromophore for rhodopsin and the cone photopigments (Probable). Required for the survival of cone photoreceptors and correct rod photoreceptor cell morphology (By similarity).
Synonyms: LCA14
Tractability: Antibody: UniProt predicts a signal peptide or a membrane-spanning region; the Human Protein Atlas places it where antibodies can reach.
Target class: Enzyme; Transferase
Gene: Protein-coding gene on chromosome 4 (154,626,945 to 154,753,120, forward strand). Ensembl gene ENSG00000121207.
Subcellular location: Endoplasmic reticulum membrane; Rough endoplasmic reticulum; Endosome, multivesicular body; Cytoplasm, perinuclear region
Subcellular location (Human Protein Atlas): Endoplasmic reticulum; Golgi apparatus; Basal body; Plasma membrane
Pathways (Reactome):
Sensory Perception: Retinoid metabolism and transport; The canonical retinoid cycle in rods (twilight vision)
Disease: Defective visual phototransduction due to LRAT loss of function
Gene Ontology:
Molecular function: phosphatidylcholine-retinol O-acyltransferase activity; protein binding; acyltransferase activity; O-palmitoyltransferase activity; acyltransferase activity, transferring groups other than amino-acyl groups; retinoic acid binding; retinol binding
Biological process: retinol metabolic process; retinoid metabolic process; vitamin A metabolic process; lipid storage; response to retinoic acid; response to vitamin A
Cellular component: endoplasmic reticulum; endoplasmic reticulum membrane; multivesicular body; perinuclear region of cytoplasm; rough endoplasmic reticulum
Genetic constraint (gnomAD): Loss-of-function variants: 11 observed, 14.99 expected, observed/expected ratio (o/e) 0.73, 90% interval 0.46 to 1.21. The upper end of that interval is the gene's LOEUF score, 1.21, which puts it in group 5 of 6, group 1 being the genes least tolerant of losing a copy. Missense variants: 274 observed, 313.94 expected, observed/expected ratio (o/e) 0.87, 90% interval 0.79 to 0.96. Synonymous variants: 144 observed, 135.67 expected, observed/expected ratio (o/e) 1.06, 90% interval 0.93 to 1.22.
Gene-disease validity (ClinGen):
ClinGen rates the evidence that LRAT causes each of these diseases.
inherited retinal dystrophy (autosomal recessive): Definitive. An instance of retinal degeneration that is caused by an inherited modification of the individual's genome.
Homologues: Orthologues: chimpanzee LRAT (100% identical), macaque LRAT (99% identical), dog LRAT (87% identical), pig LRAT (87% identical), rabbit LRAT (87% identical), guinea pig LRAT (82% identical), mouse Lrat (80% identical), rat Lrat (79% identical), tropical clawed frog lrat (59% identical), zebrafish lratb.1 (58% identical), zebrafish lrata (57% identical). Paralogues in human: PLAAT1 (20% identical), PLAAT2 (20% identical), PLAAT3 (20% identical), PLAAT5 (20% identical), PLAAT4 (19% identical), LRATD2 (17% identical), LRATD1 (16% identical).
Diseases named in the same sentence as LRAT in open-access papers:
LRAT is named in the same sentence as 26 diseases in open-access papers, as found by Europe PMC text mining. Sharing a sentence is not in itself a finding about the gene and the disease. The quoted sentences say what the papers report.
Leber congenital amaurosis (8 papers, 2007 to 2025). Leber congenital amaurosis (LCA) is a retinal dystrophy defined by blindness and responses to electrophysiological stimulation (Ganzfeld electroretinogram (ERG)) below threshold, associated with severe visual impairment within the first year of life. "Mutations in the retinoid isomerase (RPE65) or lecithin-retinol acyltransferase (LRAT) genes underlie Leber congenital amaurosis." (PMID 27920719, 2016). "Mutations in the RPE65 and LRAT genes have been associated with Leber congenital amaurosis (LCA)." (PMID 37510362, 2023). "In Leber congenital amaurosis (LCA), mutations in either lecithin-retinol acyltransferase (LRAT) or retinoid isomerase (RPE65) lead to S-opsin aggregation and subsequent ER stress, which in turn results in rapid degeneration of cone cells." (PMID 31757001, 2019). "For example, mutations in the LRAT enzyme and RPE65 isomerase lead to Leber Congenital Amaurosis (LCA), a severe early-onset blinding disease, which accounts for ~5% of all inherited retinal dystrophies." (PMID 31835521, 2019). "Leber congenital amaurosis and macular degeneration were enriched in C0, which specifically expressed RPE65, OTX2, LRAT, and BEST1." (PMID 33072724, 2020).
liver fibrosis (8 papers, 2015 to 2024). "Therefore, to understand how knockout of hepatic Surf4 affected CCl4-induced liver fibrosis, we evaluated expression of lecithin:retinol acyltransferase (LRAT), an HSC cell marker, and α-SMA, a marker for HSC activation." (PMID 39105051, 2024). "As macrophages release many cytokines and growth factors that directly impact HSCs during liver fibrosis, we ablated the Socs1 gene selectively in HSCs using the Cre recombinase expressed under the promoter of lecithin retinol acyltransferase (LRAT) involved in retinol storage in HSCs." (PMID 37860002, 2023). "The production of retinol esters (RE), which is catalyzed by lecithin-retinol acyltransferase (LRAT) and acyl-CoA retinol acyltransferase (ARAT), disappears in HSC activation and liver fibrosis." (PMID 36569303, 2022). "The genetic fate-mapping technique using lecithin retinol acyltransferase-cyclization recombination enzyme (Lrat-Cre) and PDGF receptor beta (PDGFRB)-Cre determine HSCs as the dominant source of myofibroblasts in liver fibrosis." (PMID 35971182, 2022).
retinal degeneration (8 papers, 2015 to 2025). Degeneration of the retina. "Mutations in the LRAT gene can cause early‐onset retinal dystrophy (LCA), characterized by reduced visual pigments and progressive retinal degeneration or severe blindness." (PMID 41383212, 2025). "Recent advancements in genetic analyses have revealed that mutations in some genes that are expressed in RPE, such as MERTK, RPE65, LRAT, or BEST1, cause retinal degeneration." (PMID 35504937, 2022). "Mutations in other genes expressed solely in the RPE, such as LRAT and MERTK, have been identified in patients with early-onset retinal degeneration, and mice carrying knockout (KO) mutations of these genes have the same effect." (PMID 31659211, 2019). "At the onset of retinal degeneration, the loss of ERK1/2 led to a specific decrease in the level of RPE65 with the mislocalization of lecithin retinol acyltransferase (LRAT)." (PMID 29038159, 2017). "In IRDs, retinal degeneration is caused by mutations in either genes expressed in photoreceptors or genes expressed in the adjacent RPE, as it is the case with mutations in RPE65, MERTK or LRAT." (PMID 30970664, 2019). "Potential interacting molecules involved in retinal degeneration or visual cycle, including MINDY3, EPG5, miR‐548b‐3p, OTX2, miR‐519d, LRAT, and NR2E3, were selected based on the STRING and miRDB (MicroRNA Target Prediction Database) databases." (PMID 40956390, 2025). "Mutations in several RPE-specific genes, including RPE65, LRAT (lecithin retinol acyltransferase) and MERTK (tyrosine-protein kinase Mer), have been identified in patients with early-onset retinal degeneration and LCA." (PMID 25650393, 2015).
retinal disease (4 papers, 2004 to 2019). "Deficiency in RPE65 and LRAT causes a spectrum of retinal disease that is typically classified as LCA (LCA2; OMIM #204100) or RP (RP20; OMIM 613794#), but it may include other terms such as early-onset severe rod-cone dystrophy." (PMID 26656277, 2015). "known retinal disease genes (BEST1 [NM_004183], C1QTNF5 [NM_015645], CDH3 [NM_001793], LRAT [NM_004744], RDH5 [NM_002905], RDH11 [NM_016026], RGR [NM_002921], RLBP1 [NM_000326] and STRA6 [NM_022369])." (PMID 20479888, 2010). "This is illustrated by the finding that the 15K retinome which comprises 15,645 transcripts including those which were solely found in a single study, contains an additional five of the 102 known retinal disease genes (RHOK, MTATP6, CHM, LRAT, RIMS1) not included in the 13K retinome." (PMID 15283859, 2004).
retinal dystrophies (4 papers, 2015 to 2021). "LRAT is highly expressed in the eye, and dysregulation of this gene has been associated with early onset retinal dystrophy." (PMID 33260776, 2020). "LRAT encodes an endoplasmic reticulum protein that plays an important role in the visual system; mutation in this gene is associated with severe early-onset retinal dystrophy." (PMID 31428131, 2019).
Blindness (3 papers, 2021 to 2025). Blindness is the condition of lacking visual perception defined as a profound reduction in visual perception. "LRAT−/− mice exhibit a greater than 90% reduction in retinyl ester pools and congenital blindness, highlighting LRAT’s essential role." (PMID 41463332, 2025).
retinitis pigmentosa (3 papers, 2015 to 2024). Retinitis pigmentosa (RP) is an inherited retinal dystrophy leading to progressive loss of the photoreceptors and retinal pigment epithelium and resulting in blindness usually after several decades. "This study reports a novel splicing mutation in the lecithin retinol acyltransferase (LRAT) gene associated with early onset retinitis pigmentosa and characterizes the effects of this mutation on mRNA splicing and structure." (PMID 29973277, 2018). "Mutations in the LRAT gene can cause Leber congenital amaurosis, juvenile retinitis pigmentosa, and early-onset severe retinitis pigmentosa with autosomal recessive inheritance (MIM 604863)." (PMID 29973277, 2018).
vitamin A deficiency (3 papers, 2018 to 2025). Deficiency of vitamin A due to malnutrition, malabsorption, or dietary lack. "MI was induced in mice with Stra6 germline deletion, vitamin A deficiency (VitAD) by combined lecithin-retinol acyltransferase (Lrat) germline deletion and feeding with a vitamin A-deficient diet." (PMID 41035698, 2025). "Further, we have observed an increased incidence of unsuccessful pregnancies upon β-carotene treatment of other models of embryonic vitamin A deficiency with intact carotenoid cleavage enzymes, including mice lacking both RBP4 and LRAT (Lrat−/−Rbp4−/−36; 50% unsuccessful pregnancies)." (PMID 29892071, 2018).
glioma (1 paper, 2024). A benign or malignant brain and spinal cord tumor that arises from glial cells (astrocytes, oligodendrocytes, ependymal cells). "ADH4, DHRS3, LRAT, RDH10, RDH12, and RDH5 were higher expressed in the high-glioma-risk group while DHRS9 was lower expressed." (PMID 39465792, 2024). "The prognostic signature comprised of ADH4, DHRS3, DHRS9, LRAT, RDH10, RDH12, and RDH5 based on RA metabolism was established, which provided a theoretical basis and reference value for the research of glioma." (PMID 39465792, 2024). "We identified 7 promising prognostic genes (ADH4, DHRS3, DHRS9, LRAT, RDH10, RDH12, and RDH5) within glioma and developed a prognostic model with significant predictive accuracy." (PMID 39465792, 2024). "Ultimately, ADH4, DHRS3, DHRS9, LRAT, RDH10, RDH12, and RDH5 were selected as prognostic genes for building an RA metabolism–related prognostic signature with glioma." (PMID 39465792, 2024).
Hyperglycemia (1 paper, 2018). An increased concentration of glucose in the blood. "This compound neutralized the hyperglycemia-elicited reduction of the retinoid visual cycle components of RPE65, LRAT, RDH5, CRBP, CRALBP, IRBP, and STRA6 in retina." (PMID 30096827, 2018).
myeloma (1 paper, 2017). "The other selected genes are HIST1H1E, LRAT, LCN2, KCNN4, RHOU, and EPHA5 in the order of them entering the model, among which LRAT, LCN2, RHOU, and EPHA5 are known to link to prostate cancer, and HIST1H1E and KCNN4 are connected to myeloma and pancreatic cancer, respectively." (PMID 29100492, 2017).
viral infection (1 paper, 2018). "Amongst the identified, 5 proteins (PLVAP, GKN3, EXOC8, SRC8, LRAT) were found to be up-regulated at mRNA level in both adult and P10 mouse brain post viral infection." (PMID 30082709, 2018).
tumor (6 papers, 2011 to 2025). "Expression of PDGFRα in the tumor correlated with increased collagen α1(I), lecithin retinol acyltransferase, and smooth muscle α-actin suggesting increased HSCs in tumor sites." (PMID 28465473, 2017). "The N-terminal domain (aa1–134) encodes regions that are conserved among members of the lecithin∶retinol acyltransferase (LRAT) and H-rev tumor suppressor families." (PMID 21858038, 2011). "In addition, we were able to identify different populations of tumor capsule overexpressing cancer-associated fibroblasts (CAFs) markers such as FAP, VIM, and ACTA2 as well as hepatic stellate cells markers (HGF, LRAT, RGS5)." (PMID 37932266, 2023). "Of these 13 gene candidates, three genes are already known to be tumor suppressor genes —adherens junctions associated protein 1 (AJAP1), GATA binding protein 5 (GATA5), and lecithin retinol acyltransferase (LRAT)." (PMID 33920410, 2021). "The negative correlation between the methylation status of DHRS3, LRAT, and RDH10 and their gene expression levels suggests that methylation changes could regulate the expression of key genes involved in RA metabolism, possibly altering tumor behavior." (PMID 40535799, 2025).
cancer (5 papers, 2017 to 2025). A tumor composed of atypical neoplastic, often pleomorphic cells that invade other tissues. "PLAAT4 belongs to the lecithin retinol acyltransferase (LRAT) protein family and has been proposed to suppress cancer cell invasion and metastasis." (PMID 40657374, 2025). "These genes include LRAT, MEIS1, ST8SIA1 and STC2 which have all previously been shown to be subject to transcriptional downregulation as an effect of DNA hypermethylation in human cancers." (PMID 28931069, 2017).
LRAT also shares sentences with these, for which no sentence is quoted: age-related macular degeneration (1 paper); autosomal recessive retinitis pigmentosa (1); cholestasis (1); colon cancer (1); macular degeneration (1); melanoma (1); Obesity (1); Onset (1); pancreatic cancer (1); prostate carcinoma (1); Rod-cone dystrophy (1); thyroid cancer (1).